USP13 (ubiquitin specific peptidase 13)
Diseases named in the same sentence as USP13 in open-access papers (continued):
Sharing a sentence is not in itself a finding about the gene and the disease.
ovarian carcinoma (continued). "The in vitro experiments found that the inhibition of USP13 expression could significantly inhibit the progression of ovarian cancers and enhance the sensitivity of cancer cells to treatment with PI3K/AKT inhibitors." (PMID 33194756, 2020). "USP13 promotes ovarian cancer progression by deubiquitinating and upregulating α-KGDH." (PMID 33004065, 2020). "USP13 and MCL1 were readily detectable in most ovarian cancer specimens, and analysis of consecutive tissue sections discovered a significantly positive correlation between USP13 and MCL1 expression (Spearman’s rank correlation coefficient R = 0.60, P = 2.61 × 10−4)." (PMID 29335437, 2018). "In our study, we demonstrated that USP13 is overexpressed in ovarian cancer cell lines." (PMID 28569838, 2017). "Most importantly, although BRCA1 deletion and mutation are observed in a subset of ovarian cancers, they are mostly absent in samples with USP13 amplification." (PMID 28569838, 2017). "All these results support our hypothesis that USP13 amplification in ovarian cancers may confer higher HR activity and resistance to chemotherapy." (PMID 28569838, 2017). "In addition, compared to human ovarian surface epithelial (HOSE) cells, USP13 is overexpressed in ovarian cancer cell lines." (PMID 28569838, 2017). "Our results reveal an important metabolism-centric role of USP13, which may lead to potential therapeutics targeting USP13 in ovarian cancers." (PMID 27892457, 2016). "Therefore, USP13-mediated Beclin-1 stabilization could promote autophagy of ovarian cancer under metabolic stress conditions, and it could be one of the possible mechanisms for the enhanced ovarian tumor metastasis in PTU mice." (PMID 35173307, 2022). "However, studies have also shown that USP13 may act as an oncogene by promoting Mcl-1 stability in cervical cancer, and USP13 also drives the progression of ovarian cancer by promoting cancer metabolism." (PMID 36564767, 2022). "Finally, considering that USP13 is overexpressed in ovarian cancers, a combination of USP13 inhibitor Spautin-1 and platinum-based therapy or PARP inhibitor may provide a novel approach for ovarian cancer therapy." (PMID 28569838, 2017). "The USP13 gene copy number is highly amplified in human LUSC and several other cancers, including ovarian cancer, esophageal cancer, and head and neck cancer." (PMID 38093367, 2023). "Co-inhibition of USP13 and AKT significantly decreased the viability of the primary murine ovarian cancer cells isolated from the GEMM." (PMID 35173307, 2022). "Analysis of the copy number of The Cancer Genome Atlas (TCGA) tumor samples showed that USP13 and MCL-1 were upregulated in many types of tumors, especially in lung adenocarcinoma, lung squamous cell carcinoma, ovarian cancer, and cervical cancer." (PMID 36188217, 2022). "USP13 also functions as an oncogene by stabilizing MCL1 apoptosis regulator (MCL1) in lung and ovarian cancer cells." (PMID 35173307, 2022). "In ovarian cancer (OVCA), amplified USP13 promoted core metabolic pathways by stabilizing ACLY and OGDH, providing enough ATP, reducing equivalents, and precursors for lipid biosynthesis for OVCA cell growth." (PMID 36188217, 2022). "We concluded that USP13 promoted MCL1 stability at the post transcriptional level in lung and ovarian cancer cells." (PMID 29335437, 2018). "Here we perform an unbiased siRNA screen and identify that the second deubiquitinase, USP13, regulates MCL1 stability in lung and ovarian cancer cells." (PMID 29335437, 2018).
ovarian carcinoma (continued). "To determine the protein expression and relatedness of USP13 and MCL1 in patients, we performed immunohistochemical (IHC) staining of human lung and ovarian cancer tissues." (PMID 29335437, 2018). "Collectively, these findings supported that USP13 and MCL1 were concomitantly overexpressed in human lung and ovarian cancer to promote tumorigenesis." (PMID 29335437, 2018). "In lung and ovarian cancers, where USP13 also regulates Mcl-1 stability, USP13 does not contribute to the cell proliferation of unstressed cells." (PMID 33627786, 2021). "Furthermore, USP13 can deubiquitinate and stabilise ACLY/OGDH and c-Myc in ovarian cancer and glioblastoma, respectively, thereby functioning as an oncogene." (PMID 33627786, 2021). "However, USP13 and USP30 can mediate deubiquitination of ACLY, increasing the stability of ACLY to promote development of ovarian cancer and hepatocellular carcinoma, respectively." (PMID 33004065, 2020). "Notably, gene expression of USP13 and MCL1 correlated with the genomic amplification status, indicative of their functional importance in driving lung and ovarian cancer." (PMID 29335437, 2018). "To confirm whether USP13 dictated the stability of MCL1 protein in tumor cells, we introduced two independent siRNAs against USP13 into several lung cancer (SW-1573, NCI-H441 and A549) and ovarian cancer (TOV-21G, HEY and OVCA433) cell lines." (PMID 29335437, 2018). "Consistently, western blot analysis of 22 lung cancer and 33 ovarian cancer cell lines revealed that both USP13 and MCL1, but not USP9X, were ubiquitously expressed at the protein level." (PMID 29335437, 2018). "First, USP13 promoted MCL1 protein stability in multiple lung and ovarian cancer cell models." (PMID 29335437, 2018). "The fact that the correlation between USP13 and MCL1 expression was restricted to the protein level prompted us to hypothesize that USP13 could regulate MCL1 as a deubiquitinase enzyme in lung and ovarian cancer." (PMID 29335437, 2018). "Depleting or inhibiting USP13 sensitizes ovarian cancer cells but not normal ovarian epithelial cells to cisplatin and PARP inhibitor." (PMID 28569838, 2017). "Indeed, USP13 depletion did induce a proliferation defect in some ovarian cancer cells but not others, and this was dependent on USP13 expression levels." (PMID 33627786, 2021). "Importantly, depleting or inhibiting USP13 sensitizes ovarian cancer cells to cisplatin and Poly (ADP-ribose) polymerase (PARP) inhibitor (olaparib) suggesting USP13 is a potential novel therapeutic target for ovarian cancer." (PMID 28569838, 2017). "While BRCA1 and CCDC98 are downregulated in ovarian cancer, RAP80, MERIT40 and BRCC45 are slightly amplified in ovarian cancer, but not comparable to USP13 amplification." (PMID 28569838, 2017). "By analyzing the expression levels of MCL1 and the other DUBs in nine ovarian cancer cell lines, we observed that only DUB3, and not USP9X or USP13, showed a significant positive correlation with MCL1, further supporting our hypothesis that DUB3 is the crucial DUB that modulates MCL1 stability." (PMID 32699213, 2020).
breast carcinoma (17 papers, 2015 to 2026). "Knockdown of Twist1 reversed the migration and invasion capacities of breast cancer cells and the occurrence of lung metastasis in mice caused by overexpression of USP13." (PMID 36732432, 2023). "In order to clarify the mechanisms underlying the mode of action of USP13 in breast cancer development, we first analyzed its expression in different breast cancer subclasses." (PMID 36732432, 2023). "In contrast, the loss of USP13 facilitates the proliferation, glycolysis, and anchorage-independent growth of breast cancer cells." (PMID 33195243, 2020). "Although the biochemical and molecular functions of USP13 have been explored in various human cancers, including breast cancer, the oncogenic or tumor suppressor roles of USP13 in different studies has remained controversial." (PMID 36732432, 2023). "Among the ∼100 DUBs, several members, such as A20, USP43, OTUD1, OTUD3 and USP13, have been identified as key regulators in breast cancer." (PMID 37608493, 2023). "We found that the effect of USP13 in promoting the migration and invasion capacities of breast cancer cells can at least partly be achieved through its regulation of Twist1, while Twist1 can inhibit the transcriptional activity of USP13." (PMID 36732432, 2023). "To fully explore the interplay between USP13 and Twist1, we examined the role of USP13 in inducing breast cancer cell migration and invasion through Twist1." (PMID 36732432, 2023). "Here, we investigated a potential physical/functional interaction between Twist1 and USP13 in human breast cancer." (PMID 36732432, 2023). "Scratch wound healing, cell migration and invasion assays, and a mouse lung metastases assay were used to investigate the roles of USP13 and Twist1 in promoting breast cancer metastasis." (PMID 36732432, 2023). "In contrast, in breast cancer cells, silencing USP13 can facilitate AKT phosphorylation by downregulating PTEN level, accompanied by tumor cell proliferation and glycolysis." (PMID 35445009, 2022). "For example, USP13 prevents tumor cell growth by deubiquitinating PTEN in breast cancer, OSCC and bladder cancer." (PMID 35445009, 2022). "A recent study found that USP13 stabilized PTEN expression by removing PTEN ubiquitination in human breast cancer cells." (PMID 27892457, 2016). "As a deubiquitinating enzyme of PTEN, USP13 stabilizes PTEN expression in breast cancer." (PMID 40746889, 2025). "We found that USP13 promotes breast cancer metastases through Twist1 de-ubiquitination." (PMID 36732432, 2023). "Our findings show that USP13 may play an essential role in breast cancer metastasis by regulating Twist1 and, as such, provide a potential target for the clinical treatment of breast cancer." (PMID 36732432, 2023). "The results of HE staining showed an increased proportion of nuclear atypia in lung sections of mice injected with USP13-overexpressing 4T1/Luc cells, including abnormal nuclear size and darker nuclear staining, revealing the severity of lung metastases from mammary tumors." (PMID 36732432, 2023). "However, USP13 also appears to stabilize PTEN, implicating a tumor-suppressive role for USP13, at least in breast cancer." (PMID 35173307, 2022). "Besides breast cancer, reduced USP13 expression was also detected in human bladder cancer (BC), oral squamous carcinoma (OSCC), human colorectal cancers, and testicular embryonal carcinoma." (PMID 36188217, 2022). "It was reported that USP13 acted as a deubiquitylase of PTEN in breast cancer." (PMID 26453058, 2015). "However, the underexpression of USP13 is observed in breast cancer and bladder cancer." (PMID 33195243, 2020). "USP13 suppressed tumorigenesis through deubiquitination and stabilization of phosphatase and tensin homolog (PTEN) in breast cancer." (PMID 39044157, 2024). "For example, OTUD3 and USP13 can deubiquitinate and stabilize the tumour suppressor PTEN, thereby playing a suppressing role in breast cancer." (PMID 37608493, 2023).
breast carcinoma (continued). "Through proteome‐wide screen of DUB members, USP13 and OTUD3 have been identified as deubiquitinases which directly bind to and stabilize PTEN in breast cancer." (PMID 33155366, 2021). "Nonetheless, USP13 is reported to deubiquitinate and stabilize PTEN protein, and functions as a tumor suppressor in breast cancer." (PMID 31200745, 2019). "In contrast, USP13 may act as a PTEN DUB, leading to suppressed AKT phosphorylation, glycolysis, and tumor cell proliferation in breast cancer." (PMID 41315297, 2025). "USP13 is a deubiquitinating enzyme of PTEN, and its absence in breast cancer cells may downregulate PTEN expression, thereby enhancing AKT phosphorylation." (PMID 40746889, 2025). "We found that USP13 and Twist1 can form a negative feedback loop to jointly regulate the migration and invasion of breast cancer cells." (PMID 36732432, 2023). "Taken together we found that, on the one hand, USP13 stabilizes Twist1 and, on the other hand, Twist1 inhibits USP13 promoter activation, thereby forming a negative feedback loop in breast cancer cells." (PMID 36732432, 2023). "Downregulated USP13 was correlated with PTEN levels in human breast carcinomas and overexpression of USP13 exhibited inhibitory effects on the PTEN-positive breast cancer cell line MDA-MB-231 but not the PTEN-null cell line BT549." (PMID 36188217, 2022). "Ubiquitin-Specific Protease 13 (USP13), another member of deubiquitinating enzymes (DUBs) superfamily, has been reported to deubiquitinate and stabilize PTEN and thus suppresses tumorigenesis and glycolysis in breast cancer." (PMID 31200745, 2019). "It is also noted that USP13 and PIK3CA are not amplified in breast cancer, which may interpret the tumour suppressive functions of USP13 via PTEN in breast cancer." (PMID 27892457, 2016).
melanoma (16 papers, 2014 to 2025). A malignant, usually aggressive tumor composed of atypical, neoplastic melanocytes. "In the present study, we discovered the high expression levels of USP10 and USP13 in malignant melanoma tissues and explored the function and underlying mechanisms of the anti‐melanoma effects of the USP10/USP13 inhibitor spautin‐1 through inducing the ROS‐mediated DNA damage." (PMID 32129945, 2020). "Further in vitro and in vivo studies found that AR increased MITF protein degradation by modulating miRNA‐539‐3p/USP13 signalling, which resulted in increased melanoma cell invasion by increasing the expression of the receptor tyrosine kinase AXL." (PMID 35452181, 2022). "USP13 can regulate microphthalmia-associated transcription factor (MITF), an essential modulator of melanoma growth." (PMID 35173307, 2022). "This is the only study that implicates USP13 deubiquitinase in melanoma development by regulating MITF protein stability." (PMID 35884430, 2022). "In contrast, USP13 also deubiquitinates and stabilises microphthalmia-associated transcription factor (MITF), an important lineage-specific master regulator in melanoma." (PMID 33627786, 2021). "For example, in melanoma, overexpression of miR-593-3p led to the decrease USP13 level involved in melanoma metastasis." (PMID 31952546, 2020). "USP10 and USP13 were highly expressed in malignant melanoma specimens compared to the naevus tissue." (PMID 32129945, 2020). "We have checked the expression of USP10 and USP13 in different melanoma cell lines and human skin keratinocytes cell line (HaCaT)." (PMID 32129945, 2020). "To assess the role of USP10 and USP13 in melanoma progression, we applied melanoma tissue microarray and immunohistochemistry to detect their expression." (PMID 32129945, 2020). "Knock‐down of USP10/USP13 increased cellular apoptotic rate approximately 2‐3 folds in A375 or Sk‐Mel‐28 human melanoma cells." (PMID 32129945, 2020). "We found that there were higher USP10 and USP13 expression in melanoma cell lines compared with control cells." (PMID 32129945, 2020). "Overexpression of USP13 in melanoma cells prolonged the half‐time of MITF expression in an enzymatic‐dependent manner." (PMID 28544818, 2017). "In addition, USP13 was upregulated in melanoma and pharmacological inhibition with spautin-1 or genetic knockdown of USP13 both inhibited melanoma cell growth." (PMID 36188217, 2022). "However, given the critical role of MITF in so many aspects of the developmental and therapeutic response to BRAFinh, the possibility of targeting USP13 activity as responsible for MITF stability needs to be further studied in some aspects of melanoma therapy." (PMID 35884430, 2022). "Deubiquitinase USP13 deficiency prevented the growth of melanoma in vitro and in vivo; however, MITF overexpression prevented USP13’s inhibition, indicating MITF’s involvement in melanoma development, which was mediated by USP13." (PMID 34179099, 2021). "In this study, we employed a potent USP10/13 deubiquitinating activity antagonist, spautin‐1, to investigate the effect of targeting USP10/USP13 as an anti‐melanoma treatment and found that melanoma cell proliferation was significantly suppressed by spautin‐1‐induced ROS‐mediated DNA damage." (PMID 32129945, 2020). "Further, decreased USP13 mRNA and protein expression could be detected after exposure of several melanoma cell lines to 2% O2 for 6 to 24 h." (PMID 31208103, 2019). "USP13 is essential for melanoma growth in vitro and in vivo and might be another target in MITF-mutated melanoma." (PMID 24743024, 2014). "Therefore, targeting USP13 to reduce MITF levels could suppress melanoma by inducing cell apoptosis." (PMID 36188217, 2022). "All the results suggested that USP10 and USP13 might play detrimental roles in melanoma." (PMID 32129945, 2020).
melanoma (continued). "Hence, the hypoxia-induced decrease in USP13 expression may be pathogenically important during melanoma carcinogenesis and fibroblast conversion in idiopathic pulmonary fibrosis." (PMID 31208103, 2019). "Depletion of USP13 in MITF-positive melanoma cells reduces MITF protein levels without affecting MITF mRNA levels through regulation of its ubiquitination state and the subsequent increase in MITF proteasome-mediated degradation." (PMID 35884430, 2022). "Spautin‐1 has been reported as a USP10 and USP13 antagonist, and we demonstrated that spautin‐1 has potent anti‐tumour effects as reflected by MTS and the colony formation assays in various melanoma cell lines without cytotoxic effects in HaCaT and JB6 cell lines." (PMID 32129945, 2020).
glioblastoma (9 papers, 2018 to 2025). The most malignant astrocytic tumor (WHO grade IV). "Given that USP13 regulates the stability of MYC in glioblastoma and hepatocellular carcinoma, contributing to self-renewal or tumorigenic potential, we hypothesized that USP13 would be directly associated with MYC protein abundance in lung cancer." (PMID 38093367, 2023). "For instance, USP13 deubiquitinated c-MYC in glioblastoma and lung squamous cell carcinoma to promote disease progression; USP13 oncogenically stabilized MCL-1 in ovarian and lung cancer and de-sensitized tumor cells to BH3 mimetic inhibitors." (PMID 41315297, 2025). "USP13 expression is upregulated in glioblastoma (GBM) tissues and inversely correlated with patients’ overall survival." (PMID 33195243, 2020). "In glioblastoma multiforme (GBM), USP13 was found to deubiquitinate and stabilize c-Myc, which was required for maintaining glioma stem cell (GSC) self-renewal and tumorigenic potential." (PMID 36188217, 2022). "In glioblastoma, both Spautin-1 treatment and USP10/USP13 knockdown reduce cell proliferation and migration." (PMID 40370434, 2025). "We generated hybrid co-culture models of brain organoids with four GFP+ CNS tumor cell lines, two of them representing glioblastoma (LN18 and U343-MG), and the other two representing embryonal CNS tumors (USP7-ATRT and USP13-Med)." (PMID 39599878, 2024).